MIR1244-2 (microRNA 1244-2)
Synonyms: hsa-mir-1244-2
Gene: MicroRNA gene on chromosome 5 (118,974,586 to 118,974,670, forward strand). Ensembl gene ENSG00000283498.
Homologues: Paralogues in human: MIR1244-1 (100% identical), MIR1244-3 (100% identical), MIR1244-4 (100% identical).